HMGB1 (high mobility group box 1)
Diseases named in the same sentence as HMGB1 in open-access papers (continued):
Sharing a sentence is not in itself a finding about the gene and the disease.
tumor (continued). "The result showed that the number and size of tumor spheres increased proportionally with increasing HMGB1 concentrations." (PMID 33614649, 2021). "As a result, HMGB1, which is largely produced by necrotic cells, increases in abundance as the tumor progresses." (PMID 34068946, 2021). "The higher the tumor grade, the easier to observe the cytoplasm staining of HMGB1 in more tumor cells." (PMID 34257571, 2021). "Our results indicate that the release of DAMPs such as HMGB1 from Ad-TK infected tumor cells is required for the efficacy of Ad-TK + Ad-Flt3L mediated immunotherapy." (PMID 34084145, 2021). "HMGB1 is a multi-functional protein which can be released by tumor cells post-RT, and triggers an array of DAMP-induced inflammatory responses." (PMID 33986291, 2021). "Paradoxically, in the tumor microenvironment, HMGB1 directly secreted by tumor cells renders pDCs tolerogenic." (PMID 33919546, 2021). "In the extracellular compartments, HMGB1 mediates cell proliferation, differentiation, tissue regeneration, inflammation/immune responses, and tumor progression." (PMID 33807275, 2021). "The results showed that tumor tissue significantly increased the surface expression of calreticulin and ATP and HMGB1 concentrations at 24 h after the mice treated with QD-RGD- or QD-Cat-RGD-based RT, which was consistent with the in vitro results." (PMID 34887404, 2021). "The collected evidence also states that through the induction of the high-mobility group box 1, NETs induce the epithelial to mesenchymal transition in tumor cells and, thereby, potentiate their invasiveness." (PMID 34503307, 2021). "Stimulation of the innate immune response to nucleic acids can be suppressed due to the binding of Tim-3 and HMGB1 on DCs in the tumor environment." (PMID 33868234, 2021). "In an in vitro cell model or in vivo tumor tissues, dipyridamole treatment resulted in a decline in the levels of HMGB1, RAGE, β-catenin, Runx2, YAP1, phosphorylated Smad2/3, and cyclin D1, but not TLR2 and TLR4." (PMID 33669632, 2021). "Mechanistically, KDM4D/SYVN1/HMGB1 axis modulates the tumor growth, migration and self-renewal features via promoting accumulations of HMGB1." (PMID 34820329, 2021). "In the tumor microenvironment, these DAMPs, particularly HMGB1, trigger an antitumor immune response." (PMID 34966671, 2021). "Irradiated tumor cells present calreticulin at their surface and release DAMPs, such as adenosine-5-triphosphate (ATP) and high-mobility group protein box 1 (HMGB1), that promote phagocytosis in DCs; ATP recruits DCs; HMGB1 activates DCs and CTLs." (PMID 35008367, 2021). "Regarding the underlying mechanism of the anticancer effects of dipyridamole, our findings further suggest that the tumor effect of the HMGB1/RAGE axis is a crucial target." (PMID 33669632, 2021). "The findings shed light on the anticancer role of WISP2, and HMGB1 is one of the key factors involved in the inhibition of the efficiency of WISP2 through reducing the tumour purity with fibroblast infiltration." (PMID 34497155, 2021). "The release of HMGB1 from necroptotic tumor cells that underwent ablative HFRT suggests that necroptosis induced by ablative HFRT is immunogenic and has the potential to activate immune response although there is very little direct evidence available about it." (PMID 34489957, 2021). "During tumor development and in cancer therapy, HMGB1 is released and plays multiple roles through binding receptors, including RAGE, TRL2/4, TIM3 and CXCR4." (PMID 34257571, 2021). "The secretion of HMGB1 from the nucleus to the cytoplasm is followed by HMGB1 release into the extracellular matrix of dying tumor cells." (PMID 33866918, 2021). "Macrophages can be activated by damage-associated molecular patterns (DAMPs), including high-mobility group box 1 (HMGB1), adenosine 5′-triphosphate (ATP) and double-stranded DNA (dsDNA), which are pyroptotic products of tumor cells." (PMID 34794490, 2021).
tumor (continued). "In a different biological system, the interaction of HMGB1 with an lncRNA was found to reduce degradation of HMGB1 within the cell and promote tumor cell growth." (PMID 34680084, 2021). "We observed significantly lower levels of HMGB1 in tumor extracts from the mice treated with gemcitabine and the control IgGs than in the mice treated with control IgGs alone (p = 0.03)." (PMID 33915939, 2021). "We previously reported that targeting HMGB1 with monoclonal antibodies or BoxA extends the survival of mice xenografted with human MM cells by interfering with tumor cell proliferation." (PMID 33956406, 2021). "We then cultured GBM cells with different concentrations of HMGB1, and determined the formation of tumor spheres under the neural sphere culture condition." (PMID 33614649, 2021). "The restoration of the pharmacological sensitivity of the tumour cells is favored by the increase of NF-κB activity, confirming that HMGB1 regulates drug resistance in MM cells by regulating the NF-κB signalling pathway." (PMID 34445745, 2021). "An elegant study has dissected out a pathway—essential in the study of anti-cancer immunity in mice and humans—whereby HMGB1 that is secreted by dying tumour cells activates TLR4 on dendritic cells." (PMID 34771442, 2021). "HMGB1 is also secreted from both dying tumor cells and lymphocytes, but is also released when NK cells are activated." (PMID 33777767, 2021). "Increased expression of STAT has been known to inhibit apoptosis of tumor cells, and therefore, HMGB1 activation of STAT is considered pro-tumorigenic." (PMID 34975408, 2021). "RAGE is also localized in mitochondria of tumor cells, and interaction between HMGB1 and RAGE regulates cellular metabolism and promotes tumor growth by enhancing ATP production." (PMID 33807604, 2021). "Previous reports indicate that tumor cells express RAGE, TLR-2, and TLR-4 to promote HMGB1-induced tumor growth." (PMID 34966671, 2021). "Instead, as a tumor-suppressive miRNA, exosomal miR-107 inhibits autophagy by mediating HMGB1 expression." (PMID 33917233, 2021). "Eosinophils seem to be attracted into tumors by chemotactic factors, such as eotaxins, RANTES and damage-associated molecular patterns (DAMPs, e.g., high mobility group box 1 (HMGB1)), which are released by necrotic tumor cells." (PMID 34572273, 2021). "Analysis of soluble molecules in collected cell culture supernatants revealed a dose-dependent increase in tumor-cell derived chemoattractants ATP and HMGB1." (PMID 33420228, 2021). "The MFIs of FITC-labeled anti-HMGB1 antibodies in the primary tumor tissues of SPNpro-, SPN-1-, or SPN-2-injected mice were greatly increased by 30.6-, 25.0-, and 26.7-fold relative to that for the saline-injected mice, respectively." (PMID 34006860, 2021). "High mobility group box protein 1 (HMGB1) enhances autophagic flux and protects tumor cells from apoptosis, which results in acquired drug resistance." (PMID 34778055, 2021). "Many tumor cells are also able to secret HMGB1, which, as an important component of the tumor milieu, plays a central role in cancer and metastasis development." (PMID 33919546, 2021). "GO term enrichment analysis of genes expressed at higher levels in the tumours classified as HMGB1-high showed that these include the functional terms rRNA processing, RNP biogenesis, mRNA splicing, and RNA export from nucleus to cytoplasm." (PMID 34572914, 2021). "These “danger” signals released by tumour cells include high-mobility group box 1 (HMGB1) and ATP, triggering innate and adaptive immune responses through the expression of major histocompatibility complex (MHC) class I and MHC-II molecules." (PMID 33467153, 2021). "HMGB1 functions as an extracellular signaling molecule and correlated with inflammation, differentiation, cell migration, and tumor metastasis." (PMID 34182538, 2021).
tumor (continued). "Circ_0005909 silencing reduced tumor growth and restrained cell proliferation and metastasis by inhibiting the production of high mobility group box 1 (HMGB1) in a miR-936-dependent manner." (PMID 34930332, 2021). "Pro-tumorigenic roles of HMGB1 include initiation of inflammation, enhance tumor cell proliferation, promotes tumor invasion and metastasis, enforces angiogenesis, involves in chemoresistance and promotes antitumor immunity." (PMID 34721407, 2021). "Both endogenous and exogenous HMGB1 have been suggested to be important regulators of autophagy in tumor cells." (PMID 34778055, 2021). "Released DAMPs include adenosine triphosphate (ATP), which is a chemoattractant for DC precursors, high mobility group box 1 (HMGB1), which is a maturation/activation factor for DCs, and type I interferons that attract T lymphocytes into the tumor bed." (PMID 34272360, 2021). "In our study, we found that Salmonella treatment polarizes TAMs toward an M1-like phenotype by increasing tumor secretion of HMGB1." (PMID 34829795, 2021). "MiR-218 overexpression would inhibit HMGB1-induced autophagy by restoring tumour cell response to paclitaxel." (PMID 34445745, 2021). "The prominent role of HMGB1 in this context was illustrated in murine anti-tumor vaccination models, where HMGB1 blockade abrogated therapeutic effects both in vivo and in vitro." (PMID 34025657, 2021). "Interaction between RAGE and HMGB1 promotes the activations of tumor cell signaling pathways, such as those of ERK1/2, p38MAPK, and NF-κB, and results in cancer progression and metastasis." (PMID 34199060, 2021). "Nuclear HMGB1 translocation to cytoplasm was observed both in tumor cells and vascular endothelial cells." (PMID 34257571, 2021). "High expression of HMGB1 in tumor cells mediates tumor progress through inhibition of apoptosis and elevated induction of cytoprotective autophagy." (PMID 33672622, 2021). "In a co-culture experiment employing both TLR4 and HMGB1, DCs halted the cross presentation of tumor antigens." (PMID 34588987, 2021). "It was found that tumor slices of group VIII showed the most efficient reduction of HMGB1 signals, which was only 34.8% compared to that of untreated groups via the semiquantitative analysis." (PMID 34262038, 2021). "HMGB1 is overexpressed in tumor cells and triggers inflammation, tumor migration and cell migration." (PMID 34805222, 2021). "HMGB1 was mostly expressed in tumor cells and the intensity of cytoplasmic HMGB1 varied in different HCC patients." (PMID 33661757, 2021). "CpG oligodeoxynucleotide was used to mimic irradiated tumor-released DNA fragment and HMGB1 was a DAMP released by damaged cancer cells." (PMID 34050181, 2021). "In a tumor microenvironment, hypoxia-induced release of HMGB1 induces the accumulation of anti-inflammatory M2-like (“alternatively activated”) macrophages and IL-10 production by RAGE signaling, thereby favoring tumor development." (PMID 34685561, 2021). "Using short-hairpin RNA (shRNA) to target HMGB1, a higher number of M1-polarized macrophages were found at the tumor site, indicating that HMGB1 led to the M2 polarization of recruited macrophages." (PMID 34209703, 2021). "Extracellular HMGB1 also acts as a pro-tumor protein due to its cytokine, chemokine, and growth factor activity." (PMID 34094941, 2021). "We initially only assumed tumor cell-derived HMGB1 to be the driving force of PD-1 induction in the TAMs." (PMID 34488792, 2021). "Then, extracellular HMGB1 promotes the release of cytokines such as IL-6 and Tnf-α by activating MAPKs and Stat3 pathways, which stimulates tumor cells proliferation, angiogenesis, EMT, invasion, and metastasis." (PMID 35046917, 2021). "The effects of other intercellular substances in the tumor microenvironment, such as ATP, HMGB1, IL1β, and LDH, are still uncertain." (PMID 34298833, 2021). "While HMGB1 can promote anti-tumor immune responses, it can simultaneously potentiate tumor cell survival mechanisms." (PMID 34187428, 2021).
tumor (continued). "Studies have found that the HMGB1 protein is highly expressed in diverse solid tumors, mainly through the regulation of autophagy in drug-resistant tumor cells, playing an anti-apoptotic role." (PMID 33494431, 2021). "On the other hand, a negative correlation was established between the expression of HMGB1 and tumor marker (alpha-fetoprotein (AFP))." (PMID 34583662, 2021). "In this setting, it is unclear if the increased HMGB1 levels are a reflection of the treatment response or if these levels are increased as a consequence of tumor-intrinsic features (i.e., tumor differentiation grade)." (PMID 33920544, 2021). "Other potential signals include high mobility group box 1 (HMGB1), a danger signal that has been shown to be released from dying tumor cells that is capable of inducing dendritic cell maturation and tumor regression." (PMID 33816320, 2021). "For instance, high-mobility group box 1 (HMGB1) can be secreted from dying tumor cells and detected by toll-like receptors (TLRs) and advanced glycation end products (RAGE) on dendritic cells and macrophages, leading to downstream immune responses." (PMID 34885172, 2021). "Our findings demonstrate that irradiation‐induced PGCCs contribute to tumor repopulation via neosis, in which HMGB1 is involved." (PMID 33523579, 2021). "Further experiments are required to link the H-1PV-modified localization (nuclear/cytoplasmic), abundance, and redox status of host HMGB1 to the deactivation of cGAS/STING in infected tumor cells." (PMID 34071585, 2021). "We verified the corresponding levels of HMGB1 in the transplanted tumor tissues and blood in each group of mice." (PMID 34182538, 2021). "miR-142-3p has also been identified as a microRNA that suppressed HMGB1 expression in non-small-cell lung carcinoma and glioma, therefore playing a major role in reducing tumor cell proliferation, invasion, apoptosis, and drug resistance (to cisplatin)." (PMID 34073766, 2021). "HMGB1 was found to be expressed in most tumor cells, and a higher expression of HMGB1 was observed in tumor tissues with higher grade and staging." (PMID 34257571, 2021). "Intriguingly, our results showed that HMGB1 in the extracellular space promoted PGCC‐derived neosis in tumor repopulation." (PMID 33523579, 2021). "There is accumulating evidence that targeting HMGB1 suppresses tumor progression including proliferation, invasion and metastasis." (PMID 33747917, 2021). "HMGB1 has complex functions in cancer, and it has considerable importance in tumor formation, progression, and the response to chemotherapy." (PMID 33140586, 2021). "EP has the potential roles in suppressing inflammation related tumor progressions by inhibiting the HMGB1 and corresponding downstream pathways." (PMID 34599143, 2021). "Surprising new findings in tumor biology reveal that oxidized HMGB1 (sulfonyl HMGB1) is an anti-inflammatory molecule that signals via RAGE." (PMID 34943830, 2021). "When stress or cell damage ranging up to necrosis occurs, HMGB1 is released into the extracellular environment, exerting pro-inflammatory, immuno-regulatory and pro-tumor effects through autocrine and paracrine mechanisms." (PMID 34439887, 2021). "First, we only investigated the role of exogenous HMGB1 in tumor proliferation and metastasis using PC cells." (PMID 34805222, 2021). "It has been reported that HMGB1 expression was significantly higher in TME than in adjacent non-tumor tissues." (PMID 33614649, 2021). "Aspirin inhibits platelet–tumor cell interaction and tumor metastasis by targeting tumor HMGB1 expression, release, and action." (PMID 33669632, 2021).
tumor (continued). "Platelet-tumor cell aggregates, tumor origin HMGB1, and unidentified molecules and mechanisms are likely to be active in the reciprocal crosstalk between platelets and tumor cells." (PMID 33669632, 2021). "To further confirm the role of HMGB1 in muscle wasting, we knocked down HMGB1 in CT26 cells and HMGB1-lowexpressed CT26 tumor-bearing mice showed alleviated cachexia symptoms." (PMID 34867338, 2021). "The interaction of HMGB1 with tumor RAGE was found to be important for both tumor proliferation and metastasis formation of rat C6 glioma cells and mouse Lewis lung carcinoma cells." (PMID 34572138, 2021). "Extracellular HMGB1 acts as a pro-tumor protein due to its role with cytokines and chemokines, whereas intracellular HMGB1 acts as an anti-tumor protein due to its ability to sustain genome stability." (PMID 34373756, 2021). "Cytoplasm-staining revealed that HMGB1 was present both in tumor cells and vascular endothelial cells." (PMID 34257571, 2021). "Reduced HMGB1 in hypoxic tumor sites is suggested to generate regulatory and reparative macrophages that shape an immunosuppressive tumor microenvironment." (PMID 33708206, 2021). "High-mobility group protein box1 (HMGB1) is a pivotal factor in the development and progression of many types of tumours, which is closely correlated with tumour-mediated inflammation microenvironment." (PMID 34497155, 2021). "Inhibiting HMGB1 in irradiated MB49 tumors significantly impairs infiltration of myeloid derived suppressor cells (MDSC) and tumor associated macrophages (TAMs) in the TIME, and shifts the overall tumor immune balance towards an anti-tumoral response." (PMID 33986291, 2021). "Our previous studies revealed that HMGB1 from dying tumor cells stimulated the proliferation of living tumor cells and promoted tumor repopulation." (PMID 33523579, 2021). "To confirm the stemness of tumor spheres derived from GBM cells stimulated by HMGB1, we cultured dispersed tumor spheres adherently in the presence of serum." (PMID 33614649, 2021). "The bioluminescence imaging analyses showed that HMGB1 down-regulation markedly inhibited YAP promotion effect on tumor growth." (PMID 33726796, 2021). "In vitro and vivo study found that EVO plays an effective role in suppressing tumor growth and angiogenesis, the role of which was confirmed to be related to HMGB1/RAGE axis." (PMID 34477479, 2021). "A comparison of the levels of HMGB1 in the tumor extracts by Western blot analysis revealed differences between the different treatment groups." (PMID 33915939, 2021). "In many cases, extracellular HMGB1 acts as a pro-tumor protein due to its cytokine, chemokine, and growth factor activity, whereas intracellular HMGB1 promotes drug resistance owing to the pro-autophagy activity and regulation of gene transcription." (PMID 34094941, 2021). "In line with this, we previously proposed that the sole presence of ATP leads to the silent removal of dead cells, whereas the presence of ATP together with HMGB1 or HSP90 induces the robust anti-tumor immune responses." (PMID 34485114, 2021). "With the interactions to these receptors, extracellular HMGB1 acts as an inflammatory mediator and contributes to tumor metastasis, angiogenesis and chemotherapy resistance." (PMID 33661757, 2021). "In murine tumor systems, HMGB1 foments the development of MDSC from bone marrow progenitor cells, enhances crosstalk between MDSC and macrophages by increasing MDSC production of IL-10, and reduces the expression of L-selectin on circulating T cells." (PMID 33807604, 2021). "Recently, it has been found that pyroptosis can fuel tumor progression in colorectal cancer (CRC) by increasing the expression of proliferating cell nuclear antigen through high-mobility group box protein 1 (HMGB1) release." (PMID 34429144, 2021). "In contrast, the results of the present study demonstrated that HMGB1 released from dying tumor cells mediated the process of neosis and eventually bring about tumor repopulation." (PMID 33523579, 2021).